CTSS (cathepsin S)
Diseases named in the same sentence as CTSS in open-access papers (continued):
Sharing a sentence is not in itself a finding about the gene and the disease.
cholestasis (1 paper, 2025). Impairment of the bile flow caused by obstruction within the liver, or outside the liver in the bile duct system. "Nevertheless, studies indicate that macrophage-derived cathepsin S (CTSS) can remodel the extracellular matrix and liberate bioactive matrikines, thereby indirectly promoting HSC activation and contributing to cholestasis-associated fibrosis." (PMID 41153801, 2025).
Chronic colitis (1 paper, 2020). A chronic inflammatory disease of the large intestine (colon, cecum and rectum). "Administration of recombinant CTSS into the colonic lumen produces significant nociceptive pain, similar to the pain observed in chronic colitis and elevated levels of CTSS are observed in chronic colitis." (PMID 32398133, 2020).
chronic lung disease (1 paper, 2021). According to the definitions of the American and British Thoracic Societies, including pulmonary functional tests, X-rays, and CT scans for items such as fibrosis, bronchiectasis, bullae, emphysema, nodular or lymphomatous abnormalities. "In chronic lung diseases associated with inflammation, overexpression of cathepsin S and other cathepsins may lead to increased degradation of AMPs such as defensins HBD-2 and -3, thereby favouring Mtb infection and colonization." (PMID 34421929, 2021).
eosinophilia (1 paper, 2024). "Nevertheless, our sensitivity analyses indicated that PAPP-A (in sputum and serum), and IgE (in serum only) were associated with eosinophilia irrespective of the cut-off used and that MMP 9, Cathepsin S, and BLC were consistently associated with serum neutrophilia." (PMID 38128411, 2024).
fucosidosis (1 paper, 2015). "Additional inflammatory genes including major histocompability class II, chemokine C-C motif receptor-1 and 5, cathepsin S and IL1A are upregulated in preclinical fucosidosis frontal cortex and may also be suitable candidates for monitoring responses to therapy in the future." (PMID 26537923, 2015).
gouty arthritis (1 paper, 2025). "Proteomic analysis has revealed a crucial finding: the concentration of CTSS in the synovial fluid of gouty arthritis patients is significantly elevated." (PMID 40584622, 2025). "Our findings indicated that CPI2 reduced the levels of C5a and CTSS in a dose-dependent manner in mice with acute gouty arthritis induced by MSU (P < 0.01)." (PMID 40584622, 2025). "It is further hypothesized that CTSS may affect the level of C5a by regulating complement activation, thereby influencing the progression of gouty arthritis." (PMID 40584622, 2025). "An enzyme activity inhibition assay was conducted to detect the inhibitory effect of CPI2 on cathepsin S. In an attempt to mimic human gouty arthritis, suspensions of monosodium urate (MSU) crystals were injected into the right foot pads of C57BL/6 wild-type (WT) mice and C5aR1−/− mice." (PMID 40584622, 2025). "CPI2 may alleviate gouty arthritis by reducing the level of CTSS and regulating the C5a-C5aR1 axis." (PMID 40584622, 2025). "However, CPI2 may exert its anti-gout effect by inhibiting the activity of CTSS." (PMID 40584622, 2025). "During the inflammatory process of gout, MSU crystals stimulate inflammatory cells, leading to an increase in the activity of CTSS." (PMID 40584622, 2025). "Compared with colchicine, CPI2 is superior in reducing the swelling of the footpad in acute gouty arthritis induced by MSU, increasing the activity of GSH-Px, and decreasing the levels of CTSS and C5aR1." (PMID 40584622, 2025).
HIV-1 infection (1 paper, 2025). The type species of lentivirus and the etiologic agent of acquired immunodeficiency syndrome (AIDS). "Therefore, cathepsin S could be another factor contributing to HIV-1 infection control and the resolution of inflammation." (PMID 41226631, 2025).
hyperphosphatemia (1 paper, 2019). Abnormally high level of phosphate in the blood. "Hyperphosphatemia also induced inflammation in vascular smooth muscle cells and increased the expression of matrix metalloproteinases II and IX and cathepsin S." (PMID 31533650, 2019).
invasive carcinoma (1 paper, 2024). A carcinoma that is not confined to the epithelium, and has spread to the surrounding stroma. "Cathepsin S expression was significantly higher in invasive carcinomas NST compared with invasive lobular carcinomas (high in 19.5% vs. 12.5%, p < 0.05)." (PMID 39331316, 2024).
itch (1 paper, 2021). "In such conditions, the regulatory effect of SFII on CTSS confer an advantage in AD-related itch treatment." (PMID 34208434, 2021).
kidney failure (1 paper, 2017). An acute or chronic condition that is characterized by the inability of the kidneys to adequately filter the blood. "Eight genes related to kidney toxicity, including kidney failure (CASP1, FCGR2A, FCGR2B, TLR2, TLR4, P = 0.003), damage of renal tubule (TLR2, TLR4, P = 0.01), proximal tubular toxicity (CTSS, LYZ, SLC22A5, P = 0.007) and their expression across 6 datasets were not confounded by tissue types." (PMID 28051114, 2017).
male infertility (1 paper, 2023). The inability of the male to effect fertilization of an ovum after a specified period of unprotected intercourse. "A total of five proteins (PFS males) have been used as potential markers of male infertility, namely B2M, complement-3 (C3), CFB, VNN2, and CTSS." (PMID 37969811, 2023).
Morquio A disease (1 paper, 2022). "Here we show that cathepsin S (CTSS) and elastin (ELN) can be used as biomarkers of extracellular matrix remodeling in Morquio A disease." (PMID 35620518, 2022).
Morquio A Syndrome (1 paper, 2022). "This study is the first to investigate cathepsin S and elastin levels as biomarkers to assess the severity of CVD, genotype, and phenotype in Morquio A Syndrome." (PMID 35620518, 2022).
periodontal diseases (1 paper, 2017). "Our hypothesis was that microbial and inflammatory stimuli would impact CTSS levels in periodontal cells and tissues, thereby suggesting a critical role of this autophagy-associated molecule in the pathogenesis of periodontal diseases." (PMID 29362520, 2017). "The objective of this study was to investigate whether cathepsin S is involved in the pathogenesis of periodontal diseases." (PMID 29362520, 2017). "CTSS may be an important player in the initiation and progression of periodontal diseases." (PMID 29362520, 2017). "Therefore, CTSS may be an important player in the initiation and progression of periodontal diseases." (PMID 29362520, 2017).
peripheral arterial disease (1 paper, 2022). A disorder of the arteries supplying the upper and lower extremity and the visceral organs. "In our study, Cystatin C and the Cathepsin S/Cystatin C ratio proved to be significant determinants of severe peripheral arterial disease and three-arterial-bed involvement." (PMID 35453881, 2022).
Peritoneal Fibrosis (1 paper, 2025). Disorder characterized by a wide range of structural changes in PERITONEUM, resulting from fibrogenic or inflammatory processes. "Studies have shown that PLAU and CTSS are involved in signaling pathways related to apoptosis and cell migration, which are also implicated in peritoneal fibrosis." (PMID 40620673, 2025). "However, our findings showed that SAL does not have a significant impact on the expression of PLAU or CTSS, indicating that they are not the focus of SAL in reducing peritoneal fibrosis." (PMID 40620673, 2025).
pulmonary sarcoidosis (1 paper, 2024). Sarcoidosis affecting the lung parenchyma. "CTSS, CYBB, FPR2, MNDA, TLR1, and TLR8 could be conducive to improving the diagnostic process and understanding the underlying mechanisms of pulmonary sarcoidosis." (PMID 39364409, 2024). "CTSS, CYBB, FPR2, MNDA, TLR1, and TLR8 could be conducive to improving the diagnostic process and understanding the underlying mechanisms of pulmonary sarcoidosis, and were further verified in PBMC samples using qRT-PCR." (PMID 39364409, 2024).
rectal adenocarcinoma (1 paper, 2025). "Similar correlations were discovered in rectal adenocarcinoma, where CTSS expression was positively correlated with regulatory T-cells (Rho = 0.341, P = 1.01 × 10−3) and M2 macrophages (Rho = 0.314, P = 2.62 × 10−3)." (PMID 40794185, 2025).
SARS-CoV infection (1 paper, 2025). "CTSS has been observed to play a modest role in SARS-CoV infection, and may partially substitute for cathepsin L in certain cells." (PMID 40362649, 2025).
scrapie (1 paper, 2017). A fatal disease of the nervous system in sheep and goats, characterized by pruritus, debility, and locomotor incoordination. "Although evidence suggests the existence of increased Calpain and Cathepsin S expression in scrapie mice, final proof of a pathological Calpain-Cathepsin axis activation in prion diseases is lacking." (PMID 28449707, 2017).
small cell lung carcinoma (1 paper, 2020). Small cell lung cancer (SCLC) is a highly aggressive malignant neoplasm, accounting for 10-15% of lung cancer cases, characterized byrapid growth, and early metastasis. "A recent study showed an increased and exclusive secretion of CTSS in circulating tumor cells of small cell lung cancer, which may predict distant metastasis and targeting CTSS may limit tumor dissemination to distal sites." (PMID 32398133, 2020).
Splenomegaly (1 paper, 2025). Abnormal increased size of the spleen. "Like colitis, PgLPS exposure leads to splenomegaly in wild-type mice, and this was clearly suppressed in cathepsin S-deficient mice." (PMID 41436824, 2025).
staphylococcus aureus infection (1 paper, 2025). An infectious process in which the bacteria Staphylococcus aureus is present. "The Kyoto Encyclopedia of Genes and Genomes (KEGG) analysis highlighted enrichment in pathways like phagosome, viral myocarditis, Staphylococcus aureus infection, antigen processing, and presentation in the CTSS overexpression group." (PMID 39453382, 2025).
subarachnoid hemorrhage (1 paper, 2025). A serious neurological disorder characterized by intracranial hemorrhage into the subarachnoid space. "Cathepsin S contributes to neuroinflammation and blood–brain barrier breakdown in ischemic stroke and subarachnoid hemorrhage." (PMID 40869205, 2025).
tetanus (1 paper, 2020). A serious infectious disorder that follows wound contamination by the Gram-positive bacterium Clostridium tetani. "By analyzing the formation of peptides from treatment of tetanus toxoid by recombinant human cathepsin S, an important enzyme involved in antigen processing in vivo, aberrant tetanus toxoids could be distinguished from control toxoids." (PMID 33271767, 2020).
thymoma (1 paper, 2023). A neoplasm arising from the epithelial cells of the thymus. "The combined application of cathepsin V and cathepsin S helped identify TSCC and B3 thymomas." (PMID 36797681, 2023).
tongue cancer (1 paper, 2021). A malignant neoplasm affecting the tongue. "We report that cathepsin S was more active in human oral SCC than matched normal tissue, and in an orthotopic xenograft tongue cancer model than normal tongue." (PMID 34572924, 2021).
Ureteral obstruction (1 paper, 2020). Obstruction of the flow of urine through the ureter. "Interestingly, using a model of unilateral ureteral obstruction, the authors found that CTSB or CTSL deficiency in mice exacerbates kidney fibrosis, whereas CTSS or CTSK deficiency protects it." (PMID 33379277, 2020).
tumor (300 papers, 2001 to 2026). "CTSS expression was analyzed in CRC tumor tissues and CTSS-deficient cell lines using immunohistochemistry, Western blotting, and flow cytometry." (PMID 40794185, 2025). "Our study demonstrates that resistance of mesenchymal-like TNBC cells is associated with down regulation of BIRC5 (survivin) and upregulation of CXCL8/IL-8 and M-CSF while that of epithelial tumor cells is associated with upregulation of CTSS, MCP-1 and DKK-1." (PMID 41279138, 2025). "Experiments revealed that depletion of cathepsin S in tumors leads to reduction of CCL2 and tumor-associated macrophages, demonstrating the roles of cathepsin S in altering the cellular constitution of the TME and driving tumorigenesis." (PMID 41026370, 2025). "Brain tropism is strongly associated with cathepsin S, a cysteine protease produced by both tumor cells and macrophages." (PMID 41463352, 2025). "Several reports have indicated that the up‐regulation of osteopontin, survivin, an apoptosis inhibitor, and cathepsin S is associated with tumour cell migration, invasion, progression and metastasis." (PMID 37183661, 2024). "On the other hand, high Cathepsin S expression on tumor cells associate with better TNM status and a higher survival rate of patients." (PMID 35337112, 2022). "Recent studies have found that both tumor cells and tumor-associated leukocytes are capable of producing cathepsin S, which cleaves the junctional adhesion molecule JAM-B." (PMID 33688508, 2021). "In breast, prostate, colorectal and metastatic brain cancers, cathepsin S is supplied by the tumor cells and associated stromal cells, predominantly macrophages." (PMID 34572924, 2021). "Serum CTSS is associated with increased cancer mortality, and elevated protease expression, including CTSS, is associated with poor prognosis in numerous tumor types." (PMID 32398133, 2020). "In the epithelial cells, a significant association with increased tumour stage was also observed with high CTSS expression." (PMID 31346333, 2019). "When matched with the clinical data, a significant association between increased CTSS expression and tumour grade was observed in epithelial (p=0.0004) and stromal (p<0.0001) cells." (PMID 31346333, 2019). "Relevant literature indicates that targeting cathepsin S induces tumor cell autophagy and increases microtubule-associated protein 1 light chain 3 (LC3) protein expression." (PMID 29707130, 2018). "Increased CTSS expression at the tumor site has been reported to be a result of tumor associated macrophage (TAM) recruitment, with the presence of CTSS dependent on IL-4, indicative of an M2 phenotype." (PMID 27097645, 2016). "Cathepsin S has been implicated in a variety of malignancies with genetic ablation studies demonstrating a key role in tumor invasion and neo-angiogenesis." (PMID 27097645, 2016). "The reduction in tumor progression caused by CTSS inhibition necessitates further analysis of expression in human clinical samples, to identify patients who would benefit from CTSS inhibition." (PMID 27097645, 2016). "Based on our findings, we postulate that during tumorigenesis, a proportion of secreted cathepsin S associates with the tumour cell surface." (PMID 22168338, 2011). "As we postulated that cathepsin S is translocated from its intracellular compartment to associate with the tumor cell surface prior to secretion, we examined the cell surface expression of cathepsin S across the panel of cell lines by flow cytomtery." (PMID 22168338, 2011). "Based on our findings that cathepsin S is associated to the surface of the tumour cells we engineered a human antibody with ADCC functionality." (PMID 22168338, 2011). "Cathepsin S (CTSS), a lysosomal protease, has been frequently associated with tumor immunity." (PMID 40707961, 2025).
tumor (continued). "Moreover, treatment with anti-CD8 antibodies led to a more pronounced increase in tumor weight in CTSS-proficient cells compared with that in CTSS-deficient cells, further supporting the role of CTSS in modulating cytotoxic T-cell function." (PMID 40794185, 2025). "Additionally, the results showed that CTSS inhibition enhanced anti-tumor immunity associated with CD8+ T cells in vivo and in vitro." (PMID 40707961, 2025). "In the setting of cancer, both tumor cells and tumor-associated macrophages produce cathepsin S." (PMID 34572924, 2021). "It was reported that CTSS might be a potential predictor of chemotherapy response because up-regulation of CTSS is associated with tumor progression and poor prognosis." (PMID 34199180, 2021). "Moreover, cathepsin S-mediated autophagic flux is known to induce M2-type polarization of tumor associated macrophages, which would then contribute to tumor." (PMID 32668602, 2020). "In addition, there was a significant association between high CTSS expression, and increased tumour stage (p=0.035) in the epithelial cells." (PMID 31346333, 2019). "Therefore the high CTSS expression in the IM group is most likely associated with tumour associated immune cells." (PMID 31346333, 2019). "Furthermore, these studies have associated an M2-marcophage phenotype (tumour protective), and have implicated CTSS in a modulating role via an autophagy-mediated mechanism." (PMID 31346333, 2019). "This is consistent with the increased aberrant expression of this protease in other carcinomas where as a result of pro-tumorigenic role of this protease in cancer, increased CTSS has been associated with poor outcome reported as a result of tumour associated macrophages (TAMs)." (PMID 31346333, 2019). "This suggests that expression of CTSS in epithelial cells may be associated with tumours defective in DNA damage repair, and therefore, indicates CTSS expression may be predictive of sensitivity to DNA damaging chemotherapies." (PMID 31346333, 2019). "Furthermore the binding of Fsn0503h to surface associated cathepsin S results in natural killer (NK) cell targeted tumor killing." (PMID 22168338, 2011). "Moreover, to the degree that evolutionary mechanisms underlie tumor progression, the natural selection of tumor cells may be less likely to favor the overexpression of cathepsin S if proliferation were reduced." (PMID 34572924, 2021). "Lastly, from the context of these patients receiving adjuvant therapy and as a result of its association with BL1 subgroup CTSS may be elevated in patients with defects in DNA damage repair pathways, indicating it may be predictive of tumour sensitivity to DNA damaging agents." (PMID 31346333, 2019). "In agreement with these mechanistic findings, the application of Fsn0503, a cathepsin S monoclonal antibody, was shown to reduce tumor invasion due to attenuated proteolytic activity of extracellular cathepsin S." (PMID 41026370, 2025). "This study aimed to investigate the mechanism by which CTSS mediates IL-7 secretion and its impact on anti-tumor immunity and to evaluate the potential of RJW-58 to support the anti-PD-1 antibody (αPD-1)." (PMID 40707961, 2025). "Combined depletion of cathepsin S in both tumor cells and stromal macrophages can significantly reduce the incidence of brain metastasis." (PMID 41463352, 2025). "Its proteolytic activity is associated with MHC II antigen presentation and the recruitment of tumor-associated macrophages in the TME, further implicating CTSS in the regulation of antitumor immune responses." (PMID 40794185, 2025). "Pharmacological inhibition of cathepsin S using the selective inhibitor VBY-999 significantly reduced experimental brain metastasis when administered before tumor seeding and throughout progression." (PMID 41463352, 2025). "Cathepsin S, produced by both macrophages and tumor cells, cleaves junctional adhesion molecule B (JAM-B) at the blood–brain barrier." (PMID 41463352, 2025).